INS (insulin)
Diseases named in the same sentence as INS in open-access papers (continued):
Sharing a sentence is not in itself a finding about the gene and the disease.
Insulin resistance (continued). "Since mitochondrial dysfunction is known to be closely related with the pathogenesis of insulin resistance, this result suggests a novel mechanism of coumestrol in the muscular regulation of insulin sensitivity." (PMID 36839308, 2023). "The major pathophysiology for T2D in undernourished people is impaired pancreatic insulin secretion and rapid β-cell failure as against insulin resistance observed in obese people." (PMID 37601212, 2023). "It is also broadly recognized that proinflammatory cytokines play a role in the development of insulin resistance by interfering with insulin signaling." (PMID 37525273, 2023). "Obesity, a metabolic condition, induces insulin resistance by altering the insulin signaling pathway via a state of mild inflammation." (PMID 37761454, 2023). "In this relationship, insulin levels and insulin resistance are best correlated with the severity and progression of VaD." (PMID 37873836, 2023). "Nevertheless, it is widely accepted that insulin resistance (IR) and impaired insulin secretion are key contributors." (PMID 37685672, 2023). "In the endothelium, aldosterone can enhance the upregulation and translocation of EnaC to the cell wall, which induces vascular stiffness, impairs insulin-mediated capillary recruitment, and enhances insulin resistance." (PMID 36768567, 2023). "Given the association of T2DM with obesity, elevated free fatty acids (FFA) levels lead to insulin resistance by inhibiting the insulin signaling pathway." (PMID 37630716, 2023). "Insulin resistance was measured by the oral glucose insulin sensitivity (OGIS) index, which correlates well with the reference hyperinsulinemic–euglycemic clamp technique." (PMID 38292764, 2023). "Insulin resistance develops in overweight or obese individuals when insulin action on its target tissues is compromised." (PMID 37377968, 2023). "Several epidemiologic studies propose that low vitamin D levels are related to impaired insulin secretion, insulin resistance, and glucose clearance." (PMID 37072813, 2023). "Beta cells overcome insulin resistance by producing adequate insulin, perhaps by increasing their function and mass." (PMID 37629550, 2023). "Insulin production-related genes were more influential in males while peripheral insulin resistance and inflammation related genes were more influential in females." (PMID 37291636, 2023). "This is in accordance with previous mentioned studies, since estrogens are related to insulin resistance, and thus phthalates can affect insulin signaling through Erα-mediated pathways." (PMID 37367903, 2023). "Although women with impaired fasting glucose were more obese and showed decreased beta-cell function, there were not significant correlations between incretin production and parameters of insulin secretion, insulin resistance, or obesity." (PMID 36717953, 2023). "Insulin resistance and the subsequent obesity is a sort of subtle chronic inflammation that impedes the action of insulin and hampers the release of this hormone." (PMID 36839279, 2023). "Insulin resistance is a characteristic feature of Type 2 diabetes, a condition in which tissues that usually respond to insulin have decreased sensitivity, leading to a decrease in glucose uptake." (PMID 38283440, 2023). "Chronic Type 2 Diabetes mellitus (T2DM) is a disorder described by decreased insulin section from the pancreas or increased insulin resistance." (PMID 36833019, 2023). "By diminishing peripheral insulin sensitivity and increasing gluconeogenesis, visceral fat accumulation has been demonstrated to play a significant role in the pathogenesis of insulin resistance." (PMID 37047011, 2023). "NASH patients have more severe adipose tissue insulin resistance and progressive reduction in whole-body insulin clearance compared to those with simple steatosis." (PMID 37463179, 2023).
Insulin resistance (continued). "T2DM is characterized by elevated levels of glucose circulating in blood as a consequence of compromised insulin sensitivity of cells (insulin resistance)." (PMID 37674537, 2023). "To investigate the effects of 3-OH phloretin on obesity-induced insulin resistance and glucose metabolism, we performed insulin and glucose tolerance tests in mice that had been administered 3-OH phloretin on HFD." (PMID 36838843, 2023). "Only carotid stiffness, but not aortic stiffness, was associated with serum markers of fat accumulation and metabolic impairment such as insulin, homeostatic model of insulin resistance (HOMA-IR), serum gamma-glutamyl transferase (sGGT) and uric acid." (PMID 37071447, 2023). "HOMA-IR is an approved method for evaluating insulin resistance using fasting glucose and insulin levels and is widely used in clinical practice." (PMID 36765298, 2023). "During aging, the cell stress response via Nrf2 becomes less potent but possibly not in centenarians, and there is an age-dependent increase of circulating insulin and insulin resistance." (PMID 37854186, 2023). "SRSPs can also impair glucose uptake and utilization in these tissues by interfering with insulin signaling and inducing insulin resistance." (PMID 37680899, 2023). "As described, cluster 1 was characterized by high BMI, insulin resistance, high insulin secretion, an abnormal lipid profile, and higher kidney damage, and it was labeled as “obese insulin resistant with sufficient compensatory insulin secretion” (IR-SIS)." (PMID 36769457, 2023). "Previous studies have found a beneficial role of vitamin K in improving insulin sensitivity and glucose tolerance and reducing insulin resistance through several mechanisms." (PMID 36609317, 2023). "Studies exploring more extended supplementation periods, such as six months, have shown promising effects on insulin resistance reduction and improvements in BMI and fasting serum insulin." (PMID 38024820, 2023). "Adipose tissue dysfunction also impairs the production and release of adiponectin, an adipokine with insulin-sensitizing properties, further exacerbating insulin resistance." (PMID 37374323, 2023). "A measure of 300 μg/mL Momordica charantia saponins can not only obviously improve the activity of insulin-resistant cells but also increase the consumption of glucose, which contributes to alleviating the symptoms of insulin resistance." (PMID 37091861, 2023). "in CST-KO mice, not only explains insulin resistance in CST-KO mice but also implicates that CST is necessary for the maintenance of insulin sensitivity." (PMID 37242791, 2023). "Compared with healthy controls, mice treated with DHEA displayed insulin resistance, as revealed by glucose tolerance tests (GTTs) and insulin tolerance tests (ITTs)." (PMID 37443082, 2023). "During insulin resistance, the insensitivity of cells to insulin forces more insulin production, leading to hyperinsulinemia and type 2 diabetes." (PMID 36839230, 2023). "Pancreatic beta cells initially sense increases in glucose and lead to the release of insulin and, separately, the sensitivity of cells in the body to the signal of insulin (the impairment of which can result in insulin resistance)." (PMID 37421946, 2023). "Scientists have found that JNK-specific deletion in the muscle significantly protects insulin sensitivity in HFD-fed mice in which insulin resistance was induced." (PMID 36918975, 2023). "In fact, several preclinical studies in rodents have demonstrated that estrogens activate protective effects against insulin resistance through activation of the ERα pathway in insulin-sensitive tissues." (PMID 36678314, 2023). "Insulin resistance is defined as a pathological condition characterized by decreased responsiveness or sensitivity to the metabolic actions of insulin." (PMID 37174950, 2023).
Insulin resistance (continued). "Fasting triglyceride (TG), total-, high- and low-density-lipoprotein cholesterol (TC, HDL- and LDL-C), glucose and insulin were measured 8 years postpregnancy; homeostatic model assessment for insulin resistance (HOMA-IR) and TG: HDL-C ratio were derived." (PMID 37111088, 2023). "There is therefore an urgent need for global unbiased analyses of signaling in insulin-resistant cells to pinpoint potential alterations contributing to insulin resistance." (PMID 36808134, 2023). "T2DM is the result of insulin resistance, defective insulin secretion and/or a high rate of pancreatic β-cell apoptosis." (PMID 37107334, 2023). "Traditionally, physical exercise is promoted in T2DM, where insulin action is scarce in the context of insulin resistance and/or inappropriate insulin secretion." (PMID 37998439, 2023). "The frequency of GnRH increases as a result of insulin resistance and the excessive rise in insulin levels that follows, which raises LH/FSH levels." (PMID 37383339, 2023). "T2D develops when insulin production by β-cells cannot cope with the insulin body demand provoked by insulin resistance." (PMID 37111699, 2023). "For instance, it is known that TNF-α is related to GDM by inducing adipocyte lipolysis, which can lead to a decreased insulin sensitivity by peripheral tissues, thus being considered as a biomarker for insulin resistance in pregnancy." (PMID 37367903, 2023). "Impaired glucose tolerance, insulin resistance, and insulin secretion have been reported in patients with hyperthyroidism." (PMID 37519546, 2023). "ATMs from obese animals secrete exosomes containing miRNAs that are taken up by insulin target cells, both in vitro and in vivo, which leads to cellular and systemic insulin resistance and glucose intolerance." (PMID 36994095, 2023). "Amongst women with GDM, insulin resistance is common before pregnancy, and when pancreatic beta cells are incapable of compensating for the increased need for insulin, hyperglycaemia results." (PMID 36484476, 2023). "On the other hand, the progression of T2DM is usually genetic and associated with obesity triggering a low capacity of β-cells to secrete insulin and insulin resistance." (PMID 37513684, 2023). "This hormone prevents atherosclerosis, obesity, and insulin resistance by promoting insulin secretion, tissue insulin sensitivity, muscle glucose uptake, inflammation reduction, and lipid reduction." (PMID 37432262, 2023). "Since insulin is recognized as a marker of insulin resistance, quantifying insulin in humans is of great importance for epidemiological studies and clinical practice." (PMID 38068348, 2023). "Mechanistically, smoking promotes altered body composition (i.e. increased visceral adipose tissue), insulin resistance (i.e. reduced glucose uptake), reduced beta-cell function, and impairments in peripheral insulin signaling and free fatty acid flux." (PMID 38264059, 2023). "Amplified fatty acid flux into myocardial cells due to systemic tissue insulin resistance and insulin resistance-related reorganization of cluster differentiation protein 36 (CD36) to the plasma membrane are associated with increased fatty acid oxidation." (PMID 37512552, 2023). "Before and after eight weeks, fasting blood glucose, insulin, hemoglobin A1C, insulin resistance, total cholesterol (Chol), low-density lipoprotein (LDL), high-density lipoprotein (HDL) and triglyceride were measured." (PMID 38028980, 2023). "The subsequent depletion of β-cell insulin secretory capacity results in the clinical manifestation of insulin resistance, manifesting from both relative but also absolute insulin deficiency that develops in long-standing T2DM." (PMID 37445466, 2023). "Ob/ob mice develop obesity and decreased insulin sensitivity in the muscle, adipose tissue, and liver, leading to hyperglycemia due to the development of insulin resistance." (PMID 37432173, 2023).
Insulin resistance (continued). "Most studies reporting altered insulin signaling during insulin resistance have focused on canonical insulin signaling intermediates such as AKT1,16." (PMID 36808134, 2023). "JNK activation is involved in obesity-induced insulin resistance as well as reduced compensatory insulin secretion response." (PMID 36715159, 2023). "VD regulates insulin secretion and enhances insulin sensitivity, reduces systemic inflammation thereby improving insulin resistance." (PMID 37378077, 2023). "Insulin resistance is a defective biologic response of target tissues, mainly the liver, muscle, and adipose tissue, to insulin stimulation." (PMID 37629550, 2023). "Fasting and postprandial glucose impairment are hallmarks of selective hepatic insulin resistance because deteriorating insulin signaling affects gluconeogenesis and glycogen synthesis." (PMID 37110230, 2023). "The pathogenesis of insulin resistance is complex and involves multiple molecular factors, such as insulin, insulin receptors, and signal transduction pathways." (PMID 37065747, 2023). "Supporting this finding, earlier studies have also reported that M. charantia extracts impact the enzymes involved in the glycolytic cascade, in addition to increasing insulin secretion and decreasing insulin resistance." (PMID 37111281, 2023). "Research findings showed that resveratrol lowers blood insulin levels in animals with hyperinsulinemia and insulin resistance." (PMID 37241737, 2023). "The hormonal framework for this metabolic environment is the high concentration of growth hormone (GH), the low concentration of insulin in connection with GH-dependent insulin resistance and the low concentration of IGF-1, the so-called GH-IGF-1 axis." (PMID 37835703, 2023). "On the contrary, as a preferable strategy targeting obesity and T2DM, low-calorie Mediterranean-style or low-carbohydrate dietary regimens ameliorate insulin resistance, insulin clearance, and β-cell function." (PMID 37152942, 2023). "Among the experimental groups, GW 300 showed a decrease in insulin level (p < 0.01), and even though they ate a high-fat diet, the rate of insulin secretion was regulated, and it is thought that the GW extract lowered insulin resistance." (PMID 37432154, 2023). "Lower HOMA-IR scores are suggestive of decreased insulin resistance and thus increased sensitivity to insulin, whereas higher HOMA-IR scores suggest increased insulin resistance." (PMID 36901197, 2023). "We evaluated insulin resistance and insulin secretion using the HOMA-IR and HOMA-β index, which also showed significant variations in participants within the same glucose range." (PMID 36651735, 2023). "Insulin resistance (IR) is defined as the reduced sensitivity of target cells expressing insulin receptors to insulin." (PMID 37034166, 2023). "Periods of muscle disuse lead to the substantial development of insulin resistance, i.e. impaired insulin-stimulated glucose uptake, which occurs rapidly following the removal of muscle contraction." (PMID 37873346, 2023). "A clinical study has shown that reduced blood glucose and insulin and improved insulin resistance in patients with T2D after 1 week of very low-calorie diet with 400 kcal/day or 3 weeks of diet with 500 kcal/day." (PMID 36714968, 2023). "Reduced fasting blood glucose, serum insulin levels, and homeostatic model assessment of insulin resistance (HOMA‐IR) further confirmed improved insulin sensitivity in LKO mice on HFD." (PMID 37088778, 2023). "Metabolic syndrome (MetS) is characterized by defects in insulin action and blood glucose homeostasis stemming from hyperinsulinemia and insulin resistance in the peripheral tissue." (PMID 38203217, 2023). "As type 2 diabetes is characterized by insulin resistance, insulin (INS) levels can reflect the effectiveness of drugs." (PMID 36985444, 2023).
Insulin resistance (continued). "IRAPe is inversely proportional to insulin resistance, its level will increase when insulin resistance is reduced, and insulin sensitivity is improved." (PMID 37072577, 2023). "Weight, waist circumference, BMI, insulin resistance and fasting insulin were improved after IF although HDL levels were also decreased." (PMID 37297894, 2023). "A recent study has confirmed that individuals with extra mass and FTO rs9939609 risk genotype had higher levels of BMI, total cholesterol, insulin, high-density lipoprotein (HDL) and homeostatic model assessment for insulin resistance (HOMA-IR)." (PMID 37200795, 2023). "Type 2 diabetes (T2D) is the commonest form of diabetes mellitus, arising because of defective insulin production and insulin resistance." (PMID 37039251, 2023). "While RT remains controversial in reports of insulin sensitivity, values for the insulin resistance index (HOMA-IR) are primarily related to FBG and FINS concentrations in the body." (PMID 38235388, 2023). "For instance, PPIs have been found to improve insulin resistance and increase insulin secretion, leading to lower blood sugar levels and increased insulin utilization." (PMID 37165049, 2023). "Excessive accumulation of fat will reduce insulin sensitivity, leading to secondary hyperinsulinemia and eventually insulin resistance; in addition, hyperinsulinemia will in turn promote fat synthesis, slow down fat decomposition, and aggravate obesity." (PMID 36726150, 2023). "Insulin resistance, which is rooted in fat distribution, likely contributes to lower NT‐proANP in EA individuals via elevated fasting insulin." (PMID 36905117, 2023). "As the hepatic production of both SHBG and IGF-BP1 is downregulated by insulin, their concentrations have been suggested as useful markers of insulin resistance." (PMID 37009276, 2023). "This is due to the suggestion that under conditions of insulin resistance, the inhibitory effect of insulin on lipase activity is diminished, resulting in increased free fatty acids release through lipolysis." (PMID 37420190, 2023). "This is caused by inadequate insulin production by the pancreas or the body’s inability to effectively use the insulin produced, a condition known as insulin resistance." (PMID 37892575, 2023). "We also observed that Fuc enhanced the insulin-stimulated glucose uptake via Akt activation and reversed the impairment of insulin signaling by insulin resistance." (PMID 36771210, 2023). "To further explore the mechanisms involved in the muscle GR–mediated systemic insulin resistance, we focused on early changes in plasma insulin levels." (PMID 36917179, 2023). "In particular, Bacteroides showed a positive correlation with body weight, fat accumulation (RFT, IFT, and EFT), insulin resistance (Glucose, insulin, and HOMA-IR), and triglyceride levels." (PMID 37705572, 2023). "Insulin resistance refers to a condition in which insulin is produced in the pancreas, but the bioactivity in the target organ of insulin is reduced." (PMID 36834911, 2023). "A few years ago, a study focused on 12–32 weeks old Zucker fatty rats showed that aging and obesity significantly contributed to increased peripheral insulin resistance, which further worsened the activation of the hippocampal insulin signaling cascade." (PMID 37110210, 2023). "When pregnant women have insulin resistance (IR), their cells lack the ability to use insulin, and sugar accumulates in the blood." (PMID 37799768, 2023). "The higher level of blood glutamic acid is associated with a higher Homeostatic Model Assessment for Insulin Resistance (HOMA-IR), indicating lower insulin sensitivity." (PMID 36986163, 2023). "Some previous studies performed in this area found a significant correlation between dietary insulin index and dietary insulin loud with insulin resistance." (PMID 36915133, 2023).